TNRC18 (trinucleotide repeat containing 18)
Description:
Chromatin reader involved in the silencing of endogenous retroviruses (ERV) class-I elements, such as LTR12. Specifically binds histone H3 trimethylated at 'Lys-9' (H3K9me3) deposited by SETB1 at class-I ERV and directly mediates recruitment of corepressor complexes, such as Sin3-type and N-Cor complexes, leading to ERV silencing.
Synonyms: CAGL79; KIAA1856; TNRC18A
Tractability: PROTAC: UniProt records ubiquitination sites on it; ubiquitination databases record sites on it.
Gene: Protein-coding gene on chromosome 7 (5,306,790 to 5,425,414, reverse strand). Ensembl gene ENSG00000182095.
Subcellular location: Nucleus; Chromosome
Subcellular location (Human Protein Atlas): Mitochondria; Nuclear membrane; Nucleoplasm; Cytosol
Gene Ontology:
Molecular function: chromatin-protein adaptor activity; histone H3K9me2/3 reader activity; chromatin binding
Biological process: protein localization to chromatin; transposable element silencing by heterochromatin formation
Cellular component: chromatin; chromosome; cytosol; mitochondrion; nuclear membrane; nucleoplasm; nucleus
Genetic constraint (gnomAD): Loss-of-function variants: 69 observed, 151.54 expected, observed/expected ratio (o/e) 0.46, 90% interval 0.37 to 0.56. The synonymous counts are far from expectation, so gnomAD's model fits this gene poorly and the ratio says little. Missense variants: 4,656 observed, 3,446.8 expected, observed/expected ratio (o/e) 1.35, 90% interval 1.32 to 1.38. Synonymous variants: 2,364 observed, 1,589.8 expected, observed/expected ratio (o/e) 1.49, 90% interval 1.44 to 1.54.
Homologues: Orthologues: chimpanzee TNRC18 (99% identical), macaque TNRC18 (97% identical), dog TNRC18 (88% identical), pig TNRC18 (87% identical), rat Tnrc18 (83% identical), guinea pig TNRC18 (76% identical), mouse Tnrc18 (49% identical), zebrafish tnrc18 (38% identical), tropical clawed frog tnrc18 (36% identical), Drosophila melanogaster wge (13% identical). Paralogues in human: BAHCC1 (28% identical), BAHD1 (5% identical).
Diseases named in the same sentence as TNRC18 in open-access papers:
TNRC18 is named in the same sentence as 20 diseases in open-access papers, as found by Europe PMC text mining. Sharing a sentence is not in itself a finding about the gene and the disease. The quoted sentences say what the papers report.
acute myeloid leukemia (1 paper, 2025). Acute myeloid leukemia (AML) is a group of neoplasms arising from precursor cells committed to the myeloid cell-line differentiation. "Summary of both cases of acute myeloid leukemia with NUP98::TNRC18 fusion." (PMID 40264981, 2025).
ankylosing spondylitis (1 paper, 2024). An autoimmune chronic inflammatory disorder characterized by inflammation in the vertebral joints of the spine and sacroiliac joints. "TNRC18, which was a variant associated with LP, is associated with IBD, ankylosing spondylitis, iridocyclitis, and psoriasis and is protective for autoimmune hypothyroidism, thyroiditis, and type 1 diabetes." (PMID 38776927, 2024).
atherosclerosis (1 paper, 2020). A disease characterized by the build-up of fatty material and calcium deposition in the arterial wall resulting in partial or complete occlusion of the arterial lumen. "Additionally, CD40, F11R, TNRC18, and calcium/calmodulin-dependent protein kinase type II gamma (CAMK2G) were screened out and validated using enzyme-linked immunosorbent assay (ELISA) in an independent patient cohort and immunohistochemical (IHC) staining in an atherosclerosis mouse model." (PMID 32714363, 2020).
autoimmune hypothyroidism (1 paper, 2024). "A common genetic etiology was proposed between hypothyroidism and OLP81 and our study supports this, indicating variation at nine loci (IFIH1, LPP, CEP43, TNRC18, C12orf42, TNFSF11, ST3GAL6, IL2RA, and IKZF3) that are strongly associated with both LP and autoimmune hypothyroidism." (PMID 38776927, 2024).
Coagulopathy (1 paper, 2022). "Coagulopathy was reported in GTF2I-RARA, FNDC3B-RARA, NUP98-RARA, and TNRC18-RARA-positive AML." (PMID 35494081, 2022).
gastric cancer (1 paper, 2021). A primary or metastatic malignant neoplasm involving the stomach. "Among the gastric cancer patients, all the 15 overlapping genes appear to be isolated from each other, whereas among the controls, three gene pairs (SPINT1 and GMDS, GMDS and TNRC18, and CSNK1D and RNF19B) are connected." (PMID 33596182, 2021).
leukemia (1 paper, 2025). A malignant (clonal) hematologic disorder, involving hematopoietic stem cells and characterized by the presence of primitive or atypical myeloid or lymphoid cells in the bone marrow and the blood. "Future mechanistic studies are warranted to gain profound insights into the role of the NUP98::TNRC18 fusion in leukemia pathogenesis." (PMID 40264981, 2025). "Both patients with only the NUP98::TNRC18 fusion and no other fusion genes progressed rapidly and eventually died, indicating that the NUP98::TNRC18 fusion may play a key role in the occurrence and development of leukemia." (PMID 40264981, 2025).
osteoporosis (1 paper, 2019). A condition of reduced bone mass, with decreased cortical thickness and a decrease in the number and size of the trabeculae of cancellous bone (but normal chemical composition), resulting in increased fracture incidence. "Excluding genes without known specific functions (CDC27 and TNRC18), ARID2, HEBP1, LTBP1, and PLVAP were the only significant differences in the cancer group revealed by the gene-score methodology, while DFFA, FAM193A, and VEGFA were the only significant differences in the osteoporosis group." (PMID 31747953, 2019).
cancer (3 papers, 2019 to 2025). A tumor composed of atypical neoplastic, often pleomorphic cells that invade other tissues. "On the other hand, the role of TNRC18 in cancer was still unclear." (PMID 35347147, 2022).
TNRC18 also shares sentences with these, for which no sentence is quoted: tumor (2 papers); autoimmune disease (1); Fazio-Londe disease (1); hypothyroidism (1); iridocyclitis (1); multiple sclerosis (1); Parkinson disease (1); psoriasis (1); renal fibrosis (1); thyroiditis (1); type 1 diabetes (1).